AVP (arginine vasopressin)
Diseases named in the same sentence as AVP in open-access papers (continued):
Sharing a sentence is not in itself a finding about the gene and the disease.
Hyponatremia (continued). "It has also been found that in pediatric patients with COVID-19, pain, nausea, or some drugs stimulate the direct release of AVP and thus trigger hyponatremia." (PMID 39451561, 2024). "At AVP treatment start, the serum sodium concentration for 170 study patients was 141 mmol/L (with hyponatraemia already present in 21/170 (12.4%) of patients, and among them, with moderate degree in 4/170 (2.4%))." (PMID 39594934, 2024). "In this manuscript, a novel criterion is proposed to quickly determine the physiological relevance of non‐osmotic arginine vasopressin (AVP) release, and to add nuance to hyponatremia analysis." (PMID 38584119, 2024). "There are myriad hyponatremia cases where urine is concentrated to Ou>100 mOsmol/kg by relatively low‐grade, inappropriate AVP release, while EFWC≥0 is still true (Hall & Guyton, 2016; Mount, 2018; Voets & Vogtländer, 2019)." (PMID 38584119, 2024). "Hyponatraemia (<135 mmol/L) occurred in 38.2% of patients during AVP treatment, and physicians administered a median of 10.2 mmol/kg/d [6.2–16.4] sodium during arginine vasopressin therapy." (PMID 39594934, 2024). "Another cause of SIAD in these patients can be related to pharmacological treatments, which can induce hyponatremia by stimulating the release of AVP, or by potentiating the effect of AVP on the AVPR type 2 or by a mixed action." (PMID 36831539, 2023). "There has been significant clinical interest in AVP-related ventricular dysfunction and hyponatremia and the possible benefit of AVP antagonism." (PMID 37508636, 2023). "In ICAI, persistently low concentrations of cortisol fail to suppress AVP and hyponatremia results from impaired free-water excretion, as it happens in the syndrome of inappropriate antidiuresis (SIAD)." (PMID 36967769, 2023). "Multiple neurohormonal changes generally cause hyponatremia in patients with ADHF, particularly renin-angiotensin aldosterone system (RAAS) activation to stimulate the release of arginine vasopressin." (PMID 37884881, 2023). "The main cause of hyponatremia in oncology is the Syndrome of Inappropriate Antidiuresis (SIAD), which is often related to ectopic secretion of arginine vasopressin (AVP) by tumoral cells." (PMID 38069002, 2023). "The exact etiology of hyponatremia in COVID-19 is unclear, however, inflammatory cytokines such as interlukein-1β and IL-6 induce secretion of arginine vasopressin which can cause the syndrome of inappropriate ADH secretion (SIADH) and thus hyponatremia." (PMID 37744432, 2023). "Perioperative hyponatremia, due to non‐osmotic release of the antidiuretic hormone arginine vasopressin, is a serious electrolyte disorder observed in connection with many types of surgery." (PMID 38010195, 2023). "There has been a significant interest in AVP antagonism in the past years for heart failure with hyponatremia." (PMID 37508636, 2023). "AVP, also called the antidiuretic hormone (ADH), plays a major role in heart failure associated hyponatremia." (PMID 36675801, 2023). "Although volume depletion induced by a loop diuretic can increase vasopressin levels (leading to dilutional hyponatremia), the impairment in the medullary gradient reduces the responsiveness to AVP." (PMID 36675801, 2023). "Overall, the probability that hyponatremia in a cancer patient is due to tumoral AVP secretion is >30%." (PMID 36831539, 2023). "Inappropriate AVP secretion initiated by pituitary damage that produces AVP secretion after TSS is the predominant mechanism for hyponatremia." (PMID 36615106, 2022). "Affected patients show a constitutive AVP secretion, despite plasma hypotonicity, with a subsequent increased water reabsorption in the kidney, leading to hyponatremia, refractory to salt overload." (PMID 34468821, 2022). "It is characterized by a kidney loss of sodium, leading to polyuria, intravascular volume contraction, and hyponatremia, with increased AVP levels, because of the baroreceptor-mediated stimulus." (PMID 34468821, 2022).
Hyponatremia (continued). "The mechanisms by which diuretics worsen the severity of hyponatremia are attributable to impaired renal reabsorption of solutes through a diluting mechanism and inappropriate AVP secretion." (PMID 34713389, 2022). "In contrast, others found lower ADH/AVP in myxedematous patients, explaining hyponatremia with an ADH-independent mechanism of decreased water excretion." (PMID 36187132, 2022). "Regarding the mechanisms of drug-induced hyponatremia, stimulation of AVP release and enhancement of AVP action in the kidney have been postulated." (PMID 36233678, 2022). "Loss of intravascular volume (in hypovolemic hyponatremia) and effective intravascular volume (in hypervolemic hyponatremia) activated the neurohumoral axis, leading to increased secretion of AVP, renin, angiotensin II, aldosterone, and catecholamines." (PMID 36157210, 2022). "Already some years before, it was found that hyponatremia and resulting elevated AVP blood concentrations are correlated with poor outcome and mortality in patients with community acquired pneumonia." (PMID 36434506, 2022). "AVP analogs include desmopressin and oxytocin and can induce hyponatremia by acting as V2R agonists." (PMID 36233678, 2022). "In contrast, elevated plasma AVP levels were found in a few cases of ifosfamide-induced hyponatremia." (PMID 36233678, 2022). "Increased arginine vasopressin (AVP) secretion is considered to be the most common mechanism of hyponatremia." (PMID 34558033, 2022). "Despite its extensive application in medicine, the use of AVP still has serious limitations, such as short biological half-life and lack of specificity for receptors resulting in side effects (e.g., hyponatremia, decrease of cardiac output and platelet count)." (PMID 35328489, 2022). "Hyponatremia is a common disorder most often related to free water excess relying on overstimulated or inappropriate AVP secretion." (PMID 35678906, 2022). "AVP-mediated water retention and dilutional hyponatremia are prevalent in patients with heart failure and after cardiac surgery." (PMID 35327416, 2022). "Hyponatraemia also interferes with stimulation of arginine vasopressin (AVP) release by reducing serum osmolality." (PMID 35505424, 2022). "On the other hand, elevated plasma AVP concentrations were found in a few cases of ifosfamide-induced hyponatremia." (PMID 34955900, 2021). "We therefore chose to use AVP to induce hyponatremia in rodents, to obtain an SIAD model resembling the disease observed in humans." (PMID 33436646, 2021). "Increased levels of AVP lead to hyponatremia due to excessive inflow of water through aquaporins in the tubules of the kidney." (PMID 34156969, 2021). "AVP-related disorders include several clinical conditions that can be life-threatening when hyponatremia or hypernatremia become severe." (PMID 32809080, 2021). "The minimum effective dose of AVP (30 ng/h) was therefore used to study the effects of aquaretic agents on AVP-induced hyponatremia." (PMID 33436646, 2021). "In this context, LIT01-196 can inhibit the antidiuretic effect of AVP, by increasing urine output, decreasing urine osmolality, moderately enhancing water intake, and progressively correcting hyponatremia." (PMID 33436646, 2021). "Patients with NSIAD have reduced free water excretion and concentrated urine despite hyponatremia and low or undetectable circulating AVP levels." (PMID 34880830, 2021). "Women might be more at risk of hyponatraemia because sex hormones influence the regulation of arginine vasopressin (AVP) resulting in a higher renal sodium excretion in women as shown in a study on sex differences in the regulation of AVP during hypotonic saline infusion." (PMID 33941259, 2021). "Here, the authors report that a metabolically stable apelin-17 analog, by acting at the kidney level, reduces AVP-induced antidiuresis and improves hyponatremia in rodents, demonstrating a potential approach for treating water metabolism disorders." (PMID 33436646, 2021).
Hyponatremia (continued). "Arginine vasopressin (AVP) has been recognized as an important contributor to heart failure development through water retention, hyponatremia, and arterial vasoconstriction." (PMID 34795586, 2021). "The AVP receptor antagonists as tolvaptan (TOL) correct hyponatremia by directly blocking the binding of AVP with its receptors." (PMID 32996719, 2020). "In ultramarathon runners who experienced exercise-associated hyponatremia (EAH), there was a significant positive correlation between IL-6 and AVP levels." (PMID 31670650, 2020). "The hyponatremia also seems a result of overconsumption of hypotonic fluids and fluid retention, when the athletes release inappropriately arginine vasopressin." (PMID 31686980, 2019). "Atrial fibrillation (AF) frequently coexists with congestive heart failure (HF) and arginine vasopressin (AVP) V1 receptor antagonists are used to treat hyponatremia in HF." (PMID 31530276, 2019). "Nevertheless, in both HF and liver cirrhosis patients, hyponatremia reflects a higher activity of arginine vasopressin (AVP), inducing electrolyte-free water retention by binding V2 receptors." (PMID 30205538, 2018). "The interlinking of increased secretion of arginine vasopressin (AVP)-enhanced activity of the sympathetic nervous system and the renin-angiotensin system plays a paramount factor in the development of hyponatremia." (PMID 30408132, 2018). "We report an unusual case of a premature neonate with persistent hyponatremia, markedly elevated plasma arginine vasopressin level (32.7 pg/mL), and clinical findings consistent with the syndrome of inappropriate antidiuretic hormone secretion (SIADH)." (PMID 30364227, 2018). "Exaggerated release of arginine vasopressin (AVP) is profoundly involved in impaired water excretion and related hyponatremia." (PMID 29088071, 2017). "Persistently inappropriate secretion of AVP produces impaired water excretion and hyponatremia in SIADH." (PMID 29088071, 2017). "Dilutional hyponatremia is a consequence of persistent AVP-induced water retention due to “arterial underfilling”." (PMID 29088071, 2017). "Over-secretion of AVP is managed by conivaptan, a drug of choice against hyponatremia and accumulation of water in the body." (PMID 28854286, 2017). "The impaired AVP regulation leads to a reduction of free water excretion with following hypotonic hyponatremia." (PMID 29422914, 2017). "Malignancy-related SIADH due to ectopic secretion of arginine vasopressin manifesting as euvolemic hyponatremia is most commonly seen in patients with SCLC, but can also be associated with other malignancy types." (PMID 27473121, 2016). "In this respect, literature data reported evidences about hyponatremia due to cisplatin-based chemotherapy, suggesting two possible mechanisms: stimulation of hypothalamic AVP production and damage of renal tubules with development of salt wasting syndrome." (PMID 27167519, 2016). "AVP triggers water reabsorption via the collecting ducts, thus promoting a state of body water overexpansion which, in turn, leads to hyponatremia by dilution of the plasma PNa content." (PMID 26553121, 2015). "In previous studies, rates of hyponatremia up to 44-45% have been reported with most cases caused by the paraneoplastic syndrome of inadequate antidiuretic hormone (ADH, also known as arginine vasopressin) secretion (SIADH)." (PMID 26240768, 2015). "In this setting, the primary physiopathological mechanism responsible for hyponatremia is the disconnection of AVP secretion from its usual osmotic and hemodynamic stimuli." (PMID 26553121, 2015). "In the renal collecting duct, the aquaporin-2 (AQP2) water channel is regulated by sustained elevation of AVP release, and this leads to augmented hydroosmotic action of AVP, that results in exaggerated water retention and dilutional hyponatremia." (PMID 26239456, 2015).
Hyponatremia (continued). "In the renal collecting duct both short-term and long-term regulation of AQP2 is activated by sustained elevation of AVP, participating in renal water retention and dilutional hyponatremia." (PMID 26239456, 2015). "AVP acts through V1a and V2 receptors to trigger hyponatremia, vasospasm, and platelet aggregation which can exacerbate brain edema." (PMID 26275173, 2015). "In fact, clinical investigations have pointed out subtle defects in the maximum urinary dilution and free water clearance in patients with polydipsia and hyponatremia, perhaps in relationship with an enhanced sensitivity to arginine vasopressin." (PMID 26553121, 2015). "Other approaches, such as albumin infusion and the use of vaptans—which act by specifically antagonizing the effects of AVP on the V2 receptors located in the kidney tubules—have been evaluated for their role in the management of hyponatraemia." (PMID 24760233, 2014). "The development of hyponatremia is multifactorial and is thought to be primarily due to drug-induced excessive thirst and secretion of arginine vasopressin in the setting of fluid availability." (PMID 24942782, 2014). "Although AVP undoubtedly plays a major pathophysiological role in the development of hyponatremia in cirrhosis, it has to be outlined that another pathogenetic mechanism is involved." (PMID 26237020, 2014). "Additional systemic hypotension due to cardiovascular regulatory compromise activates the release of vasopressor hormones, among them AVP, leading to hyponatremia due to SIADH." (PMID 26237593, 2014). "This study was further strengthened by the fact that patients also had sequential measurements of AVP and BNP performed, to confirm the cause of hyponatremia." (PMID 26237593, 2014). "Although the pathophysiological process of hyponatremia is complex, AVP is a common etiologic factor." (PMID 24558627, 2013). "Hyponatremia often results from an increase in circulating arginine vasopressin (AVP) levels and/or increased renal sensitivity to AVP, combined with an increased intake of free water." (PMID 24558627, 2013). "That is, during normal physiology, the development of hyponatraemia ought to suppress AVP release and to result in a maximally dilute urine with a low urine osmolality." (PMID 22280539, 2012). "As initially reported at the time of NSIAD diagnosis, serum AVP was undetectable with concurrent hyponatremia, serum hypoosmolality, and inappropriately concentrated urine." (PMID 22325688, 2012). "AVP levels were undetectable (< 1 pg/ml) on initial presentation with hyponatremia during infancy, leading us to the identification of an activating V2R mutation." (PMID 22325688, 2012). "NSIAD was subsequently described in two infant boys presenting with seizures due to severe hyponatremia and high urinary osmolality, but low plasma AVP levels." (PMID 22518188, 2012). "Because the physiological stimulus for AVP release is hypertonicity, elevated AVP or copeptin levels in the context of hyponatraemia indicate a pathological setting." (PMID 22280539, 2012). "Symptomatic children, however, typically present with clinical and biological features suggesting inappropriate antidiuretic hormone secretion with severe hyponatremia and high urine osmolality, but a low plasma arginine vasopressin level." (PMID 22518188, 2012). "In the present study, serum copeptin levels were evaluated in a large cohort of patients with imported malaria to further explore the role of AVP in the pathophysiology of hyponatraemia in malaria." (PMID 22280539, 2012). "The evidence for the pathogenetic role of AVP in the pathophysiology of hyponatraemia in malaria is substantial." (PMID 22280539, 2012). "Chronic elevation of AVP, which regulates both urinary concentration and excretion, can disrupt normal homeostatic correction of this hyponatremia." (PMID 22732834, 2012). "Hyponatraemia has been attributed to high and possibly inappropriate arginine vasopressin secretion in severe malaria." (PMID 15526044, 2004).
Hyponatremia (continued). "CONCLUSION: This case illustrates a dual-hit mechanism- stress-associated non-osmotic arginine vasopressin secretion with inappropriate antidiuresis (SIAD-like physiology) on a low-solute background-leading to acute symptomatic hyponatraemia." (PMID 41688911, 2026). "AVP plays a role in the hyponatremia and volume overload seen in congestive heart failure." (PMID 40217758, 2025). "The main mechanism causing hyponatraemia is increased secretion of arginine vasopressin (AVP) as a result of perioperative non-osmotic stimuli—such as pain, nausea, and surgical stress—that reduce the excretion of free water." (PMID 39505591, 2025). "The syndrome of inappropriate antidiuresis (SIAD), characterized by nonosmotic release of arginine vasopressin, is a typical cause of hyponatremia." (PMID 40584812, 2025). "Similarly, downregulation of ZO-1 mRNA was observed in acute hyponatremia-induced by both AVP (p < 0.05, n = 8) and dDAVP (p < 0.05, n = 5), vs. Sham group (n = 6)." (PMID 40603486, 2025). "Interestingly, excessive AVP secretion is a known complication of subarachnoid haemorrhage, leading to hyponatremia in the syndrome of inappropriate antidiuretic hormone secretion (SIADH), for which the ACOM is the most commonly affected site." (PMID 41341140, 2025). "The Syndrome of Inappropriate Antidiuretic Hormone Secretion (SIADH) is a paraneoplastic condition characterized by hyponatremia, serum hypo-osmolality, and inappropriately concentrated urine due to the ectopic production of arginine vasopressin (AVP) by tumor cells." (PMID 41395606, 2025). "Also, the more severe the hyponatremia, the more readily should any degree of AVP release be considered abnormal." (PMID 38584119, 2024). "Here, the AVP release is “concurrent” rather than “sufficient”, as it cannot in itself cause hyponatremia, which necessarily leads to the diagnosis of multifactorial hyponatremia." (PMID 38584119, 2024). "It is speculated that hyponatremia primarily exacerbates intestinal wall damage by activating arginine-vasopressin and antidiuretic hormone, leading to water retention." (PMID 39435385, 2024). "Drinking over thirst and nonosmotic release of arginine vasopressin (AVP) are 2 major drivers claimed to be responsible for the fluid volume excess observed in exercise-associated hyponatremia." (PMID 38312776, 2024). "As half of the patients in this study cohort received furosemide in parallel to AVP, this might have aggravated hyponatraemia." (PMID 39594934, 2024). "Interestingly, individuals experiencing hyponatremia associated with CBZ or OXC use have shown both elevated and reduced levels of AVP." (PMID 38707045, 2024). "As will be argued in this report, these two are not necessarily synonymous (even though any degree of inappropriate AVP release naturally contributes to the occurrence and/or the perpetuation of hyponatremia to some extent, since renal water clearance would be more efficient if it were absent)." (PMID 38584119, 2024). "It has been reported in many publications that hyponatremia may be due not only to hypovolemia, but also to some hypothalamic arginine vasopressin secretion stimulation." (PMID 39064448, 2024). "The most common cause of hyponatremia in cancer patients is SIADH, which may result from tumors secreting arginine vasopressin, and it is most frequently observed in lung cancer." (PMID 39850569, 2024). "Further, both studies observed persistent hyponatraemia after the cessation of AVP." (PMID 39594934, 2024). "Moreover, arginine vasopressin, released due to low cardiac output, augments intravascular volume, contributing to hyponatremia development in HF patients." (PMID 39076508, 2024). "Consequently, AVP antagonist administration emerges as a critical component of integrated long-term management for hyponatremia in HF cases." (PMID 38204798, 2023).